BDNF (brain derived neurotrophic factor)
Diseases named in the same sentence as BDNF in open-access papers (continued):
Sharing a sentence is not in itself a finding about the gene and the disease.
Alzheimer disease (continued). "ACSL3 mitigates Alzheimer’ s disease pathology by activating the brain-derived neurotrophic factor (BDNF) and vascular endothelial growth factor C (VEGF-C) signaling pathways, with its underlying mechanism potentially linked to the synthesis of ω−3 and ω−6 FAs." (PMID 41288931, 2025). "Under stress conditions, such as the early stages of neurodegeneration seen in Alzheimer’s disease (AD), serum BDNF levels may increase as a compensatory mechanism to mitigate neurodegeneration." (PMID 40867851, 2025). "Moreover, Tau downregulates BDNF in Alzheimer’s disease mouse models, while Alzheimer’s patients carrying the BDNF val66met polymorphism show increased Tau levels and Tau phosphorylation." (PMID 40715999, 2025). "Beyond Alzheimer’s disease, increased BDNF expression may also confer neuroprotective effects in Parkinson’s disease by supporting the survival and function of dopaminergic neurons in the substantia nigra pars compacta." (PMID 40944272, 2025). "Similarly to aging, individuals with Alzheimer’s disease exhibit decreased BDNF mRNA levels in the hippocampus, and reductions in BDNF exacerbate Alzheimer’s disease-related memory dysfunctions." (PMID 40715999, 2025). "Consequently, BDNF signaling pathways have been investigated as a prospective objective for the advancement of innovative therapeutic drugs for Alzheimer’s disease treatment." (PMID 40325262, 2025). "A significant decrease in the pro-BDNF level was shown in Alzheimer’s disease." (PMID 40003962, 2025). "The role of BDNF on ageing, is also controversial as a number of studies have shown that increased BDNF may be found in Alzheimer’s Disease and conditions leading to accelerated biological ageing." (PMID 41219904, 2025). "As an example, BDNF signaling pathway upregulation through epigenetic regulation has been noted to reduce amyloid-beta accumulation and improve cognitive function in models of Alzheimer’s disease." (PMID 41283454, 2025). "Additionally, due to its crucial function in synaptic plasticity, brain-derived neurotrophic factor (BDNF) is one of the prospective therapeutic targets in Alzheimer’s disease (AD)." (PMID 41550299, 2025). "As a sulfated polysaccharide derived from red algal extract, carrageenan can regulate the expression of BDNF, and some studies have explored the effects of different molecular weight λ-carrageenans on Aβ-induced memory impairment in a rat model of Alzheimer’s disease." (PMID 40710500, 2025). "BDNF concentrations in the brain and blood are involved in the development of Alzheimer’s disease." (PMID 39513900, 2024). "As expected, in addition to experimental research studies, clinical evidence also shows that the alteration in BDNF levels in neurodegenerative diseases can be a promising biomarker in most neurodegenerative conditions and neurodegenerative diseases, including Alzheimer’s disease (AD)." (PMID 38338875, 2024). "BDNF expression is decreased in patients with Alzheimer’s disease (AD)." (PMID 38257270, 2024). "Our results align with previous studies showing that caffeine increases BDNF expression in the hippocampus, a brain region crucial for learning and memory, as well as in a mouse model of Alzheimer’s Disease." (PMID 39617850, 2024). "Additionally, research suggests that in Alzheimer's disease (AD), BDNF acts by inhibiting neuroinflammation and glial cell activity." (PMID 39648800, 2024). "Many studies have evaluated circulating BDNF levels in both plasma and serum, assuming that they were correlated to BDNF levels in the brain, and have reported altered levels in several neurological and psychiatric disorders such as mood disorders, schizophrenia, and Alzheimer’s disease." (PMID 39062102, 2024). "(2018) reported that aspirin could upregulate the expression of BDNF and other members of the neurotrophin in a mouse model of Alzheimer's disease." (PMID 39262160, 2024).
Alzheimer disease (continued). "Interestingly, in the early phase of Alzheimer’s disease, a transient increase was found in the serum BDNF levels, which significantly decreases during the progression of the disease in correlation with the severity of dementia." (PMID 37994990, 2024). "Further research may be needed to better understand the relationship between changes in BDNF mRNA levels in the brain and serum levels, as well as their impact on cognitive function and the progression of Alzheimer’s disease." (PMID 39513900, 2024). "In addition, BDNF plays an important role in neuroprotection by reducing Aβ toxicity in Alzheimer’s disease (AD)." (PMID 39594453, 2024). "In Alzheimer's disease, reduced BDNF levels contribute significantly to cognitive decline." (PMID 39568824, 2024). "Decreased levels of BDNF have been observed in the hippocampus and in cerebrospinal fluid in disease states with cognitive decline, including Alzheimer’s disease, indicating that decreased BDNF signaling may contribute to this cognitive decline." (PMID 38353689, 2024). "Dysregulation of the BDNF/TrkB pathway is commonly observed in CNS diseases such as Alzheimer’s disease, Parkinson's disease, and stroke, and microglial-expressed BDNF is critical for regulating synaptic transmission and plasticity during recovery from these diseases." (PMID 37962460, 2024). "Furthermore, in vitro studies have demonstrated that the upregulation of miR22 in brain tissues of rats with Alzheimer's disease leads to a downregulation of expressions of brain‐derived neurotrophic factor (BDNF) and apoptosis‐related proteins." (PMID 39086110, 2024). "The inverse correlation between BDNF and inflammation markers and the increased BDNF in the MCP group supported by the results of this study show that MCP may be an essential potential agent for use in the treatment of Alzheimer’s disease." (PMID 39727960, 2024). "This study not only provides a good discussion of the vast literature surrounding BDNF protein expression in Alzheimer's Disease models but also provides valuable insight into how AD-related changes to BDNF protein expression are not only brain region but also cell type specific." (PMID 38164567, 2024). "Our work characterizes a novel BDNF mimetic with preferable pharmacological properties and neurogenic and neuroprotective actions in Alzheimer’s disease via stem cell-based screening, demonstrating the promise of stem cell systems for short-listing competitive candidates for further testing." (PMID 38971770, 2024). "Linalool showed potential in improving cognitive performance of Alzheimer’s disease models, with a mechanism potentially involving the decrease of acetylcholinesterase activity and an increased expression of brain-derived neurotrophic factor (BDNF) and the tropomyosin kinase B (TrkB) receptor." (PMID 38999870, 2024). "Interestingly, several of these SNPs are in genes implicated in Alzheimer's disease (AD), such as apolipoprotein E (ApoE), catechol‐O‐methyltransferase (COMT), and brain‐derived neurotrophic factor (BDNF)." (PMID 38234228, 2024). "The results showed that Alzheimer’s disease reduced the concentration of BDNF." (PMID 39484298, 2023). "A decrease in the serum levels of BDNF has been observed in patients with Alzheimer’s disease." (PMID 37569815, 2023). "Biomarkers of neuroprotection, for e.g., brain-derived neurotrophic factor (BDNF), insulin-like growth factor 1, and neurofilaments (NFs), as well as Alzheimer's disease-related biomarkers, for e.g., amyloid-β 42, phosphorylated tau, and total tau, are gaining ground." (PMID 38098628, 2023). "Quetiapine was found to improve the decrease in BDNF-positive cells in the basolateral amygdala and hippocampus of transgenic models of mice with Alzheimer’s disease through its modulating effects on neuroprotective factors such as reducing demyelination and increasing BDNF." (PMID 37605729, 2023).
Alzheimer disease (continued). "Furthermore, it has been demonstrated that downregulation of the BDNF/TrkB system and chronic stress have a role in the pathogenesis of Alzheimer’s disease (AD) and mental disorders." (PMID 37781095, 2023). "Therefore, there is a great potential for therapeutics that will enhance BDNF/TrkB signaling in a wide range of different diseases, including Alzheimer’s disease." (PMID 37446337, 2023). "This could open new therapeutic avenues for the use of BDNF-loaded chitosan microspheres in models of CNS pathology, such as Parkinson’s, Alzheimer’s disease or spinal cord injury therapies." (PMID 36827132, 2023). "Furthermore, a relationship between pro-BDNF signaling and PPARβ/δ was reported in Alzheimer’s disease in vitro and in vivo models." (PMID 37226204, 2023). "Additionally, BDNF can protect against amyloid beta (Aβ) toxic effects and tau hyperphosphorylation in Alzheimer’s disease, despite concurrent Aβ-mediated suppression of BDNF mRNA." (PMID 37299458, 2023). "Brain-derived neurotrophic factor (BDNF) has not been validated as a diagnostic marker for Alzheimer's disease (AD)." (PMID 37009109, 2023). "Alzheimer’s disease (AD), the most common form of dementia among older adults, often involves synaptic and neuronal degeneration of the hippocampus, and one of the areas where BDNF is expressed is the hippocampus nuclei." (PMID 36970903, 2023). "Thus, potential therapeutic benefits of BDNF has been studied widely in Alzheimer's disease, stroke, and depression." (PMID 36329115, 2022). "A similar correlation of BDNF levels has been observed in patients with Alzheimer disease." (PMID 35668928, 2022). "Brain-derived neurotrophic factor (BDNF) has a protective role in Alzheimer’s disease (AD)." (PMID 36498925, 2022). "Thus, YG exerted neuroprotective effects by activating ERK/CREB/BDNF signaling in the hippocampus, indicating its potential cognition-enhancing effects, especially in Alzheimer’s disease." (PMID 36386241, 2022). "Therefore, the low-molecular-weight BDNF mimetic GSB-214 dipeptide eliminatesinduced memory impairment in rats in the scopolamine- andstreptozotocin-induced models of Alzheimer’s disease." (PMID 36694902, 2022). "Notably, for other neurodegenerative disorders, including Parkinson’s disease (PD) and Alzheimer’s disease (AD), exercise-induced BDNF has been proposed as a protective factor." (PMID 35239684, 2022). "Donepezil, a cholinesterase inhibitor used for the treatment of Alzheimer's disease, increased serum BDNF in Alzheimer's disease patients, while atorvastatin, a HMG-CoA reductase inhibitor, increased serum BDNF levels and improved functional recovery following stroke." (PMID 35283994, 2022). "Furthermore, in patients with Alzheimer’s disease, CSF irisin and BDNF are directly correlated with amyloid-β pathology and cognition." (PMID 35627690, 2022). "New endogenous PPARα ligands have been isolated in hippocampal neurons, and one of these ligands, hexadecanamide, upregulates BDNF expression in hippocampal neurons, thus promoting synaptic functions and plasticity, as reported in a mouse model of Alzheimer’s disease (AD), the 5XFAD mouse." (PMID 35625650, 2022). "It is clear that BDNF levels change in patients with Alzheimer’s disease (AD)." (PMID 35741616, 2022). "Diverse and region-specific dysregulation of BDNF-TrkB signaling has been observed in many neuropsychiatric disorders such as Alzheimer’s disease (AD), Parkinson’s disease, Amyotrophic Lateral Sclerosis (ALS), Huntington’s disease, epilepsy, stroke, mood disorders and schizophrenia." (PMID 35321093, 2022). "This BDNF also influences neural survival and differentiation, and prevents neuronal damage and death, and decreased levels of BDNF have been observed in germ-free (GF) mice, and in the brains and serum of patients with Alzheimer’s disease." (PMID 34948234, 2021).
Alzheimer disease (continued). "Collectively, these findings suggest that the consequences of HFD-induced reductions in BDNF could be early contributors to Alzheimer’s disease progression." (PMID 34017238, 2021). "Furthermore, zinc supplementation in the 3xTg mouse model of Alzheimer's disease was found to prevent cognitive decline through increasing BDNF levels and mitigating tau, amyloid, and mitochondrial Alzheimer's disease-associated pathology." (PMID 33597269, 2021). "In addition, rutin can promote the expression of a brain-derived neurotrophic factor in the hippocampus, promising a potent alternative therapeutic agent for Alzheimer’s disease." (PMID 34959916, 2021). "Indeed, the gene and protein expression of BDNF is severely reduced in the hippocampus and temporal and frontal cortex regions in Alzheimer disease brain." (PMID 33643008, 2021). "BDNF is a neurotrophin promoting cell survival and synaptic plasticity which plays a key role in pathogenesis of different neurodegenerative diseases, such as Alzheimer’s disease." (PMID 34073241, 2021). "In the course of some diseases, such as Alzheimer disease, and during aging process or chronic stress, the inhibition of BDNF expression is noted, while exercise, enriched environment, and taking antidepressants are related to the intensified expression of BDNF." (PMID 33572550, 2021). "Although BDNF rs56164415 was not confirmed to be associated with Alzheimer’s disease (AD) in a meta-analysis, it was associated with altered executive function in AD patients, and a reduction in neurocognitive function in T allele carriers." (PMID 33926045, 2021). "Furthermore, elevated brain level of miR-206 was reported in the mouse model of Alzheimer’s disease (AD), whereas its reduction enhanced the synthesis of BDNF and improved memory function." (PMID 32050617, 2020). "Given the critical role of BDNF in neural processes, BDNF Val66Met may affect brain and cognitive functioning in the context of ageing and Alzheimer’s disease." (PMID 32218234, 2020). "Furthermore, decreased BDNF expression in the brain tissue of humans with Alzheimer's disease and the animal models of the disorder has been reported." (PMID 32454931, 2020). "Furthermore, patients with Alzheimer’s disease have been reported to have a positive correlation between BDNF concentrations and their MMSE-J score." (PMID 32957612, 2020). "In conclusion, this study showed that tDCS application in 5xFAD mice, a genetic animal model designed as a disease model, induces LTP response via the continuous production of pCREB, CREB, and BDNF and presented a mechanism for memory enhancement in Alzheimer’s dementia." (PMID 32806774, 2020). "Moreover, we will review data that illustrate the role of BDNF as a potent protective factor that is able to confer protection against neurodegeneration, in particular in Alzheimer’s disease." (PMID 33096634, 2020). "Furthermore, ICS II significantly improved the functions of learning and memory in Alzheimer's disease (AD) mice and upregulated BDNF/TrkB signaling in paralleled vitro study." (PMID 32390851, 2020). "For example, expression levels of BDNF and TrkB.FL are decreased, whereas TrkB.T1 is increased in Alzheimer’s disease, with suggestions that this change may at least partially be mediated by amyloid-beta plaques in a calpain-dependent mechanism." (PMID 32403409, 2020). "It is relevant to say that the most prominent pathological characteristic in Alzheimer's disease is the degeneration of the hippocampus network, and the fact that BDNF plays a protective role in attenuating amyloid-related toxicity makes it as a perfect candidate for early diagnosis." (PMID 33269104, 2020). "This study aims to compare the effect of 9-weeks continuous (CAT) to interval aerobic training (IAT) on brain derived neurotrophic factor (BDNF) plasma level, aerobic fitness, cognitive performance, and quality of life among senior with Alzheimer’s disease (AD)." (PMID 31921371, 2020).
Alzheimer disease (continued). "For instance, the insufficient level of BDNF has a vital role in the development and pathology of Alzheimer’s disease, Parkinson’s disease, and Huntington’s disease, while recombinant BDNF improves cognition and increases hippocampal synapse density in mice model of Alzheimer’s disease." (PMID 30341248, 2019). "Considering that MMP causes the production of mature neurotrophins, we can speculate that Cu2+ and its complex with NGF mimetic peptides contribute to counteract the differential deregulation of NGF and BDNF found in Alzheimer’s disease." (PMID 30939824, 2019). "It is also reported that LIPUS can stimulate the intact rat brain circuitry and promote expression of brain-derived neurotrophic factor (BDNF), which can regulate the long-term memory, to protect aluminium salt-induced cortex injury in Alzheimer’s disease model." (PMID 30341248, 2019). "The observed properties include inhibition of apoptotic events, anti-inflammatory effects, reduced glutamate release in pathologic conditions, modulation of BDNF, reduction of oxidative stress, and improvement of cognitive capacity in a model of Alzheimer’s disease." (PMID 31727149, 2019). "BDNF is known to be a neurotrophic protective factor, involved in the regulation of several critical neuronal functions and neuroplasticity in patients who suffer nervous system diseases such as Parkinson’s disease, Alzheimer’s disease, and stroke." (PMID 31635269, 2019). "It has been reported that expression of BDNF decreased in patients with Alzheimer's disease." (PMID 31114535, 2019). "Although there are few studies about the relation between pioglitazone and BDNF, it is known that memory impairment, BDNF disturbance and oxidative damage induced by β-amyloid in an animal model of Alzheimer's disease are reversed by chronic administration of pioglitazone." (PMID 31036753, 2019). "Several studies reported a deregulation of the expression of BDNF by alterations of DNA methylation and non-coding RNA in different neurological diseases, such as Alzheimer’s disease (AD), Parkinson’s disease (PD), Huntington’s disease (HD) and amyotrophic lateral sclerosis (ALS)." (PMID 31454921, 2019). "The polyphenol protective effects against neurodegeneration are consistent with their therapeutic role on specific neurological disorders as is the case for the Alzheimer’s disease (AD) in which they afford neuroprotection via activation of brain-derived neurotrophic factor (BDNF)." (PMID 31380366, 2019). "In the present study, the intrahippocampal injection of exogenous GQ1b was mainly carried out to reveal neurological functions of GQ1b-induced BDNF expression on Alzheimer’s disease mouse model because it is hard to manipulate specific regulation of endogenous gangliosides by genetic intervention." (PMID 31186474, 2019). "The signaling of brain-derived neurotrophic factor (BDNF) has been suggested to be impaired in Alzheimer’s disease (AD), which may compromise the function of BDNF upon neuronal activity and survival." (PMID 30774582, 2019). "AAV2/1 has been utilized to target neurons for anti-inflammatory effects of dominant-negative chemokine CCL2 mutant, interleukin-10 (IL-10) in mouse models of Alzheimer’s Disease (AD) and brain-derived neurotrophic factor (BDNF) in rat models of Huntington’s Disease." (PMID 29244806, 2017). "Reduced expression of brain-derived neurotrophic factor (BDNF) has a crucial role in the pathogenesis of Alzheimer's disease (AD), which is characterized with the formation of neuritic plaques consisting of amyloid-beta (Aβ) and neurofibrillary tangles composed of hyperphosphorylated tau protein." (PMID 27701410, 2016). "Based on our current findings, we anticipate that fucoxanthin might exhibit great therapeutic efficacy for the treatment of Alzheimer’s disease by acting on multiple targets, including inhibiting AChE and increasing BDNF expression." (PMID 27023569, 2016).